TMED3 (transmembrane p24 trafficking protein 3)
Diseases named in the same sentence as TMED3 in open-access papers (continued):
Sharing a sentence is not in itself a finding about the gene and the disease.
prostate carcinoma (continued). "Functional gene ontology annotations for the genes co-expressed (R >0.5 and P<0.001) with AIM1, ERGIC1, TMED3 or TPX2 in clinical prostate cancer samples (n = 66–329)." (PMID 22761906, 2012). "Collectively, these results suggested that TMED3 knockdown could be an important defense mechanism against prostate cancer development." (PMID 39735675, 2025). "The present findings imply that TMED3 is a novel inducer of prostate cancer progression, and its downregulation may hold prognostic value for metastasis." (PMID 39735675, 2025). "However, compared with mice injected with shCtrl cells, mice injected with TMED3-downregulated prostate cancer cells showed lower prostate cancer metastasis in vivo on day 23 after the treatment." (PMID 39735675, 2025). "Transmembrane emp24 trafficking protein 3 (TMED3) is associated with the development of several tumors; however, whether TMED3 regulates the progression of prostate cancer remains unclear." (PMID 39735675, 2025). "The present findings suggested that TMED3 inhibition may serve as a potent therapeutic target against prostate cancer progression." (PMID 39735675, 2025). "TMED3 inhibition suppressed prostate cancer cell metastasis in vivo and in vitro." (PMID 39735675, 2025). "In the present study, we found that TMED3 was highly expressed in prostate cancer cells." (PMID 39735675, 2025). "In this study, we found that TMED3 protein levels increased in prostate cancer cells, and TMED3 knockdown inhibited the proliferation, migration, and invasion and promoted the apoptosis of prostate cancer cells in vitro." (PMID 39735675, 2025). "Moreover, this study associates ERGIC1 and TMED3 expression with ERG oncogene expression, supporting their potential in the management of prostate cancer." (PMID 22761906, 2012). "However, the involvement of TMED3 in the pathophysiological progression of prostate cancer cells and the potential molecular mechanisms remain unclear." (PMID 39735675, 2025). "The present results suggest that TMED3 serves as a potential tumor-promoting gene that enhances the proliferation and metastasis of prostate cancer, and TMED3 inhibition may be a useful therapeutic target against prostate cancer." (PMID 39735675, 2025). "Therefore, we hypothesized that the TMED3-induced phosphorylation of FOXO1a and FOXO3a may regulate the proliferation, migration, invasion, and apoptosis of prostate cancer cells." (PMID 39735675, 2025). "We investigated whether TMED3 downregulation alleviated prostate cancer in mice." (PMID 39735675, 2025). "TMED3 is involved in multiple pathways that may contribute to prostate cancer development." (PMID 39735675, 2025). "First, we observed the levels of the TMED3 protein in normal human prostate cells (RWPE-1 cells) and prostate cancer cells (DU145, PC-3, and LNCap cells)." (PMID 39735675, 2025). "Thus, the results indicated that TMED3 may play a crucial role in prostate cancer progression." (PMID 39735675, 2025). "Short hairpin RNA was performed to repress TMED3 in prostate cancer cells (DU145 cells) and in a prostate cancer mice model to determine its function in prostate cancer in vitro and in vivo." (PMID 39735675, 2025). "Finally, we determined whether TMED3 downregulation alleviated prostate cancer development in vivo." (PMID 39735675, 2025). "The mRNA expression of AIM1, ERGIC1, TMED3, and TPX2 was studied in six prostate cancer (VCaP, PC-3, MDA-PCa-2b, LNCaP, DU145 and 22Rv1) and three non-malignant prostate epithelial cell lines (RWPE-1, PrEc, EP156T)." (PMID 22761906, 2012). "Due to the function of AR as an important oncogene in prostate cancer, the effect of AIM1, ERGIC1, TMED3, and TPX2 expression on AR signaling was analyzed." (PMID 22761906, 2012). "Taken together, these results suggest that the expression of the potential novel drug targets AIM1, ERGIC1, TMED3, and TPX2 is promoted by ERG oncogene and androgens in cultured prostate cancer cells." (PMID 22761906, 2012).
prostate carcinoma (continued). "Thus, the results indicated that TMED3 inhibited the FOXO pathway by inducing FOXO1a and FOXO3a phosphorylation during prostate cancer progression." (PMID 39735675, 2025). "In order to illustrate the potential of the selected putative targets in the treatment of hormone-refractory disease, the efficacy of AIM1, ERGIC1, TMED3, and TPX2 silencing in the inhibition of prostate cancer cells cultured in androgen deprived conditions was studied." (PMID 22761906, 2012). "The reason behind TMED3 activation in prostate cancer was not clarified." (PMID 39735675, 2025). "However, evidence on the role of TMED3 in prostate cancer is lacking." (PMID 39735675, 2025). "In addition, although ERGIC1 and TMED3 were highly expressed in both ERG negative and positive prostate cancers, their mRNA expression levels positively correlated with ERG expression levels in ERG positive samples (P = 0.002 and P = 0.007 respectively)." (PMID 22761906, 2012).
chordoma (5 papers, 2021 to 2025). Chordomas are rare malignant tumors arising from embryonic remnants of the notochord in axial skeleton. "Although the molecular mechanisms by which TMED3 promotes chordoma progression are not fully understood, evidence shows that TMED3 plays these functions through activating PI3K/AKT signaling and inhibiting apoptosis and MAPK9/JNK2 signaling pathways." (PMID 35805075, 2022). "Consistently, in patients with chordoma, which was considered as a low-grade tumor derived from axial skeleton, TMED3 was also found overexpression in tumor cells." (PMID 35854294, 2022). "Recently, accumulating evidence reported that TMED3 exerts a protumor function in non-small cell lung cancer, lung squamous cell carcinoma and chordoma cells." (PMID 34838013, 2021). "TMED3 has also been proposed as a potential therapeutic target for the treatment of chordoma, a rare low-grade bone axis tumor; downregulation of TMED3 expression decreased chordoma cell survival and migration and increased apoptosis." (PMID 37928880, 2023).
gastric cancer (4 papers, 2022 to 2025). A primary or metastatic malignant neoplasm involving the stomach. "It has been suggested that TMED3 is involved in chemotherapy resistance during the treatment for gastric cancer." (PMID 35854294, 2022). "Through targeting TMED3, miR-876-3p modulates the resistance of gastric cancer cells to cisplatin and their stem-like properties." (PMID 36467881, 2022).
lung squamous cell carcinoma (4 papers, 2021 to 2023). "TMED3, as an intracellular transporter, was knocked down to induce abnormalities in apoptosis-related proteins in lung squamous cell carcinoma (LUSC) cells." (PMID 35754792, 2022). "TMED3 played a role in promoting the progression and development of lung squamous cell carcinoma, liver cancer, and breast progression, and TMED8 methylation was a novel predictive and prognostic feature for patients with high-risk neuroblastoma." (PMID 35754792, 2022).
glioma (3 papers, 2023 to 2025). A benign or malignant brain and spinal cord tumor that arises from glial cells (astrocytes, oligodendrocytes, ependymal cells). "Through single-cell sequencing, we can gain a clearer understanding of TMED3's function in different glioma cell subpopulations." (PMID 40471367, 2025). "In vivo experiments further confirmed that high TMED3 expression promotes glioma initiation and progression." (PMID 40471367, 2025). "Further comparative analysis of glioma cluster 0 with adjacent normal tissues highlighted TMED3 as a differentially expressed gene in GBM, as shown in the heatmap and volcano plot analyses." (PMID 40471367, 2025). "Using an in vitro TMED3 knockdown model, we assessed the impact of TMED3 on key malignant phenotypes of glioma cells, including proliferation, invasion, migration, and apoptosis." (PMID 40471367, 2025). "The integrated application of these technologies helps to deepen our understanding of the role of TMED3 in gliomas, providing a theoretical foundation and experimental support for the development of targeted TMED3 therapeutic strategies." (PMID 40471367, 2025). "In conclusion, this study reveals the crucial role of TMED3 in the initiation and progression of gliomas and uncovers its potential molecular mechanisms." (PMID 40471367, 2025). "Several recent studies have shown an increased expression of TMED3 in a number of cancers and TMED3 promotes the carcinogenesis of liver, breast, colorectal, lung, and endometrial cancer as well as glioma and osteosarcoma." (PMID 36769103, 2023). "After validating the impact of TMED3 on the growth, migration, invasion, and apoptosis of GBM cells through in vitro experiments, we further investigated its role in glioma initiation and progression using in vivo models." (PMID 40471367, 2025).
non-small cell lung carcinoma (3 papers, 2021 to 2023). A group of at least three distinct histological types of lung cancer, including non-small cell squamous cell carcinoma, adenocarcinoma, and large cell carcinoma. "Besides, it was proposed that TMED3 enhanced Wnt/β-catenin signaling by regulating AKT to exert a tumor-promoting function in non-small cell lung cancer." (PMID 35854294, 2022). "TMED3 is a protein that is highly expressed in non-small cell lung cancer (NSCLC) tissues, and high TMED3 levels indicate that a patient's chance of survival will be lowered." (PMID 37928880, 2023).
osteosarcoma (3 papers, 2021 to 2023). A usually aggressive malignant bone-forming mesenchymal neoplasm, predominantly affecting adolescents and young adults. "In conclusion, we have revealed a vital role for TMED3 in osteosarcoma, and our clinical analyses point the prospect of TMED3 as a diagnostic marker for osteosarcoma." (PMID 34838013, 2021). "The biological function of TMED3 in osteosarcoma was determined through loss-of-function assays in vitro." (PMID 34838013, 2021). "In this study, the potential biological function and underlying mechanism of TMED3 in progression of osteosarcoma was elaborated." (PMID 34838013, 2021). "Moreover, a series of loss-of-function experiments revealed the promoting role of TMED3 on osteosarcoma cell growth, migration and tumor formation." (PMID 34838013, 2021). "In vitro studies revealed that TMED3 knockdown prevented the growth of osteosarcoma by reducing proliferation and migration and increasing apoptosis, whereas TMED3 knockdown prevented the formation of osteosarcoma in vivo." (PMID 37928880, 2023). "Combined with GEO database and immunohistochemical staining on the tissue microarray chip, identified that TMED3 is overexpressed in osteosarcoma." (PMID 34838013, 2021). "In the present study, we found that knockdown of TMED3 inhibited the behaviors of osteosarcoma cells on inhibiting proliferation, impeding migration and enhancing apoptosis." (PMID 34838013, 2021). "Based on the GEO database, we further analyzed that TMED3 expression profiles of tumor and normal samples from osteosarcoma patients." (PMID 34838013, 2021). "Knockdown of TMED3 inhibited the progression of osteosarcoma by suppressing proliferation, impeding migration and enhancing apoptosis in vitro." (PMID 34838013, 2021). "The expression of TMED3 in osteosarcoma was significantly higher than that in normal tissues (P < 0.001)." (PMID 34838013, 2021). "Consistently, the expression levels of TMED3 in human osteosarcoma cells (U-2OS, Saos-2, MNNG/HOS, MG-63) was higher than the osteoblast cells hFOB 1.19." (PMID 34838013, 2021). "Taken together, TMED3 was not only highly expressed in patients with osteosarcoma, but also positively correlated with the malignancy degree." (PMID 34838013, 2021). "TMED3 was identified as a potential target of Ribosomal protein S15A (RPS15A) among the regulated downstream genes in osteosarcoma." (PMID 34838013, 2021). "The simultaneous knockdown of RPS15A and TMED3 intensified the inhibitory effects on osteosarcoma cells in terms of proliferation, apoptosis and migration." (PMID 34838013, 2021). "Comprehensive analysis validated that downregulation of TMED3 inhibited the progression of osteosarcoma by inhibiting proliferation, migration and enhancing apoptosis in vitro." (PMID 34838013, 2021). "More importantly, knockdown of RPS15A alleviated the promotion effects of TMED3 overexpression in osteosarcoma cells." (PMID 34838013, 2021). "Subsequent the loss/gain of function experiments showed that knockdown of RPS15A alleviated the promotion effects of TMED3 overexpression in osteosarcoma cells, especially in proliferation, colony formation, apoptosis and migration." (PMID 34838013, 2021). "The increased expression of TMED3 indicated the deepening of tumor malignancy in patients with osteosarcoma." (PMID 34838013, 2021). "According to the TARGET-OS database, the expression of RPS15A and TMED3 in osteosarcoma was significantly positively correlated through Spearman analysis." (PMID 34838013, 2021). "The loss-of-function assays explained that the inhibitory effects of RPS15A knockdown on the progression of osteosarcoma cells was similar to that of TMED3." (PMID 34838013, 2021). "Further investigations elucidated that the simultaneous knockdown of RPS15A and TMED3 intensified the inhibitory effects on osteosarcoma cells." (PMID 34838013, 2021). "The molecular mechanism of the regulation of TMED3 on osteosarcoma was determined by gene expression profile analysis." (PMID 34838013, 2021).
osteosarcoma (continued). "Analogously, in order to determine the effects of RPS15A and TMED3 on osteosarcoma, experimental groups of TMED3 + NC-shRPS15A, shRPS15A + NC-TMED3, TMED3 + shRPS15A and shRPS15A + shTMED3 were established in MNNG/HOS cells." (PMID 34838013, 2021). "Although the diverse characters of TMED3 in tumor progression have been increasingly recognized in recent years, whose potential mechanism in osteosarcoma is still mystical." (PMID 34838013, 2021). "The expression of TMED3 in osteosarcoma tissues was significantly greater than that in matched adjacent normal tissues." (PMID 34838013, 2021). "Notably, the pro-moter impact of TMED3 overexpression in osteosarcoma cells was reduced by downregulating RPS15A." (PMID 37928880, 2023). "Furthermore, protein S15A (RPS15A) was discovered to be a downstream target of TMED3 that contributes to the development of osteosarcoma." (PMID 37928880, 2023). "The expression of TMED3 in osteosarcoma was analyzed by immunohistochemical staining." (PMID 34838013, 2021). "The potential mechanism of TMED3 in osteosarcoma cells was further explored." (PMID 34838013, 2021). "The effect of TMED3 downregulation on osteosarcoma was further explored by xenograft tumor model." (PMID 34838013, 2021). "The present study found that knockdown of TMED3 could upregulated Caspase3 expression in osteosarcoma cells." (PMID 34838013, 2021). "Accordingly, the relationship between RPS15A and TMED3 in osteosarcoma aroused our interest." (PMID 34838013, 2021). "Collectively, our data showed that TMED3 acted as a tumor promoter in osteosarcoma." (PMID 34838013, 2021). "Additionally, ribosomal protein S15A (RPS15A) was determined as a potential downstream target for TMED3 involved in the progression of osteosarcoma." (PMID 34838013, 2021). "In this study, we determined the overexpression of TMED3 in osteosarcoma tissues relative to normal tissues by IHC analysis and explored the relationship between TMED3 and clinicopathologic feature in patients with osteosarcoma." (PMID 34838013, 2021). "Importantly, knockdown of RPS15A alleviated the promotion effects of TMED3 overexpression in osteosarcoma cells." (PMID 34838013, 2021). "The proliferation, clone number, apoptosis and migration ability of osteosarcoma cells were estimated to evaluate whether TMED3 is involved in the regulation of osteosarcoma." (PMID 34838013, 2021). "We further validated that knockdown of TMED3 inhibited osteosarcoma generation in vivo." (PMID 34838013, 2021). "Moreover, the preliminary molecular mechanism by which TMED3 knockdown induced apoptosis in osteosarcoma cells was elucidated using human apoptotic antibody array." (PMID 34838013, 2021). "Furthermore, knockdown of RPS15A alleviated the promotion effects of TMED3 overexpression in osteosarcoma cells." (PMID 34838013, 2021). "Besides, the preliminary molecular mechanism by which TMED3 knockdown induced apoptosis in osteosarcoma cells was initially explored." (PMID 34838013, 2021). "Subsequently, the mechanism of TMED3 regulating osteosarcoma was analyzed by microarray analysis." (PMID 34838013, 2021). "In this study, our attention firstly focused on TMED3 expression in osteosarcoma." (PMID 34838013, 2021). "However, the role of TMED3 in osteosarcoma remains mysterious." (PMID 34838013, 2021). "Moreover, osteosarcoma patients with high expression level of TMED3 had shorter survival period." (PMID 34838013, 2021). "Taken together, the downregulation of TMED3 could inhibited the osteosarcoma formation in vivo." (PMID 34838013, 2021). "Further research revealed that the inhibitory effect on osteosarcoma cells was enhanced by simultaneous knockdown of RPS15A and TMED3." (PMID 37928880, 2023). "Collectively, our study indicated that TMED3/RPS15A axis played vital roles in osteosarcoma progression and which might become a potential therapeutic target for osteosarcoma treatment." (PMID 34838013, 2021).
osteosarcoma (continued). "In summary, these findings emphasized the importance of TMED3/RPS15A axis in promoting tumor progression, which may be a promising candidate for molecular therapy of osteosarcoma." (PMID 34838013, 2021). "Therefore, we suspected that TMED3 may modulate the apoptotic signaling via targeting RPS15A and regulating its activity in osteosarcoma, which certainly still warrants our further investigation." (PMID 34838013, 2021). "Therefore, TMED3/RPS15A axis may play a role in promoting the development and progression of osteosarcoma, which may provide a blueprint for the therapeutic target of osteosarcoma." (PMID 34838013, 2021).
renal cell carcinoma (3 papers, 2019 to 2022). "From survival analysis, we found a very good marker (TMED3) to predict the prognosis of renal cell carcinoma patients." (PMID 31057605, 2019). "TMED3 was identified as a prognostic biomarker of renal cell carcinoma, since higher TMED3 expression levels were found in high-stage and -grade cohorts when compared to low-stage and -grade cohorts." (PMID 31878985, 2019). "TMED3 was identified as a new prognostic biomarker because its expression was increased in the high-stage and -grade cohorts compared to the low-stage and -grade cohorts in renal cell carcinoma." (PMID 35754792, 2022).
endometrial carcinoma (2 papers, 2022 to 2023). A malignant tumor arising from the epithelium that lines the cavity of the uterine body. "In a word, this study demonstrated overexpression of TMED3 in endometrial carcinoma cells and TMED3 depletion significantly inhibited tumor progression both in cell and animal models through limiting growth and migration but promoting apoptosis of EC cells." (PMID 35854294, 2022).